SESN1 (sestrin 1)
Diseases named in the same sentence as SESN1 in open-access papers (continued):
Sharing a sentence is not in itself a finding about the gene and the disease.
Hypertension (1 paper, 2020). The presence of chronic increased pressure in the systemic arterial system. "In the present study, the plasma levels of the antioxidant proteins Sesn1, Sesn2, and Sesn3 in hypertension patients were detected." (PMID 32626541, 2020). "Plasma Sesn1 levels were significantly increased in hypertension patients when compared with the control group and gradually increased between the grade I, grade II, and grade III groups." (PMID 32626541, 2020). "The results of our study revealed that Sesn1, Sesn2, and Sesn3 levels were significantly increased in hypertension patients when compared with the normotensive subjects." (PMID 32626541, 2020). "This study is aimed at investigating the level of circulating Sesn1, Sesn2, and Sesn3 in hypertension patients." (PMID 32626541, 2020). "In conclusion, we found that plasma Sesn1, Sesn2, and Sesn3 levels were increased in hypertension patients and positively correlated to the blood pressure values." (PMID 32626541, 2020). "Therefore, this study is aimed at examining plasma Sesn1, Sesn2, and Sesn3 levels in hypertension patients." (PMID 32626541, 2020). "Nondipper hypertension patients exhibited higher plasma Sesn1, Sesn2, and Sesn3 levels when compared to dipper hypertension patients." (PMID 32626541, 2020). "Furthermore, plasma Sesn1, Sesn2, and Sesn3 levels were positively correlated to both SBP and DBP in hypertension patients." (PMID 32626541, 2020). "Compared with the normotensive subjects, Sesn1, Sesn2, and Sesn3 levels were increased in patients with hypertension, with a gradual increase between the groups with grade I, grade II, and grade III hypertension." (PMID 32626541, 2020). "Moreover, Sesn1, Sesn2, and Sesn3 levels were elevated in patients with dipper hypertension and further increased in patients with nondipper hypertension." (PMID 32626541, 2020).
leukemia (1 paper, 2023). A malignant (clonal) hematologic disorder, involving hematopoietic stem cells and characterized by the presence of primitive or atypical myeloid or lymphoid cells in the bone marrow and the blood.
maxillary cancer (1 paper, 2024). "Suppression of SESN1 reduces cisplatin and hyperthermia resistance through increasing reactive oxygen species (ROS) in human maxillary cancer cells." (PMID 38322112, 2024).
myocardial ischemia (1 paper, 2022). A disorder of cardiac function caused by insufficient blood flow to the muscle tissue of the heart. "In contrast to Sestrin 1, Sestrin 2 is activated under hypoxic conditions induced by ischemic injury as most widely characterized by myocardial ischemia/reperfusion injury." (PMID 36252128, 2022).
osteosarcoma (1 paper, 2024). A usually aggressive malignant bone-forming mesenchymal neoplasm, predominantly affecting adolescents and young adults.
Skeletal muscle atrophy (1 paper, 2023). The presence of skeletal muscular atrophy (which is also known as amyotrophy). "Notably, SESN1 levels were reduced in the serum of elderly human individuals, implying that SESN1 could function as a potent circulating biomarker to predict progressive skeletal muscle atrophy." (PMID 37199024, 2023).
tumor (24 papers, 2012 to 2025). "Therefore, the deficiency of SESN1 or SESN2 supports the growth of tumor xenografts and potentially contributes to cancer progression, but their role in carcinogenesis is poorly understood." (PMID 39985075, 2025). "Similar to scRNA-seq, the expression levels of MDM2 and SESN1 in patients with tumor increased significantly after surgery." (PMID 40335909, 2025). "The loss of SESN1 and SESN2 in A549 lung adenocarcinoma cells facilitates tumour growth and enhances resistance to apoptosis." (PMID 40361504, 2025). "Overexpression of SESN1 had an anti‐tumor effect that decreased NB cell proliferation, cell migration, and cell invasion in vitro, and low expression of SESN1 means poor prognosis for patients with NB." (PMID 38516781, 2024). "Compared with control siRNA‐transfected group, knockdown SESN1 promoted NB tumor growth and shortened the tumor‐bearing mice survival time." (PMID 38516781, 2024). "In this study, we demonstrate that MYCN regulated the expression of SESN1 in NB cells, and SESN1 regulated the cell proliferation, cell migration, and invasion of NB cells in vitro, and tumor growth and NB tumor‐bearing mice survival in vivo." (PMID 38516781, 2024). "MYCN regulated the expression of SESN1 in NB cells, and knockdown SESN1 increased NB cell proliferation, cell migration, and cell invasion in vitro, and promoted NB tumor growth and shortened tumor‐bearing mice survival time in vivo." (PMID 38516781, 2024). "The genes encoding SESN1 and SESN2 proteins are potential candidates for tumor suppressors in the lung." (PMID 31857853, 2019). "Therefore, SESTRINs may suppress proliferation and support cell death in cancer cells in response to nutrient deficiency and cytokines and the signals associated with SESN1/2-dependent cell death may also stimulate an immune response aiming to eradicate tumor cells." (PMID 31857853, 2019). "Although inactivation of Sesn2 in mice led to inhibition of tumor growth, inactivation of either SESN1 or SESN2 in A549 cells stimulated cell proliferation and protected cells against cell death induced by glucose starvation." (PMID 31857853, 2019). "SESN1 functions as a new tumor suppressor gene in NB via a MyD88‐dependent TLR signaling pathway." (PMID 38516781, 2024). "SESN1 functions as a new tumor suppressor gene via TLR signaling pathway in NB." (PMID 38516781, 2024). "Our study indicates SESN1 functions as a new tumor suppressor gene via a MyD88‐dependent TLR signaling pathway in NB, and SENS1 and TLR signaling pathway may be new therapy targets for NB clinical treatment." (PMID 38516781, 2024). "Knockdown SESN1 promoted tumor growth and shortened tumor‐bearing mice survival time." (PMID 38516781, 2024). "Additionally, knockdown SESN1 promoted tumor growth and shortened the survival time in xenograft mouse model." (PMID 38516781, 2024). "KEGG enrichment analysis showed PD‐L1 expression and PD‐1 checkpoint pathway in cancer was another pathway enriched in all of the four cell lines transfected with SESN1 siRNA #1 and siRNA #2, and NB was a typical “cold tumor” with an impressive immune microenvironment." (PMID 38516781, 2024). "Additionally, we compared the time of tumor appearance and found that tumors appeared significantly earlier in the SESN1 knockdown group than that in the control group." (PMID 38516781, 2024). "Furthermore, the body weight of SESN1‐knockdown mice decreased along with the tumor growth, indicating that SESN1 silencing exacerbated the disease state." (PMID 38516781, 2024).
tumor (continued). "NAP1L5 and SESN1 have been shown to act as tumor suppressors in previous studies on cancer." (PMID 37667226, 2023). "RT-qPCR, western blot, cell counting kit-8 (CCK-8), EdU (5-Ethynyl-2'-deoxyuridine) staining, LC3 staining, ROS (reactive oxygen species) detection, and apoptosis assays were conducted to explore the effects of sestrin 1 on KGN human granulosa-like tumor cells." (PMID 33883304, 2021). "Inactivation of SESN1/2 may give cancer cells additional advantages to survive in the harsh conditions of tumor-host interactions." (PMID 31857853, 2019). "While we observed that expression of SESN1 and SESN2 is often decreased in human tumors, inactivation of Sesn2 in mice positively regulates tumor growth through a mechanism associated with activation of AKT, while knockout of Sesn1 has no additional impact on carcinogenesis in Sesn2-deficient mice." (PMID 31857853, 2019). "The important role of SESN1/2 in the facilitation of cell death in A549 cells is in contrast with our previous data, obtained on immortalized mouse embryonic fibroblasts and some tumor cell lines." (PMID 31857853, 2019). "Therefore, we propose that SESN1&2 may act as tumor suppressors in lung and other cancer types by suppressing aberrant STAT3 activation, protecting against uncontrolled cell proliferation, and maintaining cell death." (PMID 39985075, 2025). "Collectively, these results indicate that SESN1 is a downstream target of MYCN and functions as a tumor suppressor gene in NB." (PMID 38516781, 2024). "Disabling SESN1 and/or SESN2 in A549 cells amplifies cell growth and bestows resistance to cell death under glucose scarcity, thereby fostering early tumor expansion." (PMID 39759146, 2024). "The upstream regulator analysis of cisplatin revealed an increase in FAS, BTG2, SESN1, and CDKN1A, and the involvement of the tumor microenvironment pathway." (PMID 38003016, 2023). "Patients with low tumor expression of GNG12, HBP1 and SESN1 genes presented reduced OS and worse RFS, compared to patients with high expression of these genes." (PMID 34681793, 2021). "For instance, miR-21 directly targets tumor suppressive PTEN, SESN1, CAB39L, and RASA1 in different types of cancer to regulate different cancer cell behaviors." (PMID 31500623, 2019). "Sestrin 1 (SESN1), a putative tumor suppressor and mTOR signaling inhibitor, was identified as a gene synergistically up-regulated commonly in 3 of 4 EZH2 mutant cells with combination treatment, but not in EZH2 wild-type cells." (PMID 25493630, 2014). "The repression affects known tumor or metastasis suppressor genes, such as TRIM 29, ACVR1B, and LPAR6, and the sestrins, SESN1 and SESN3; however, in our analyses, ACVR1B, LPAR6, and sestrins were not validated by the qNPA method." (PMID 22276141, 2012). "SESN1 belongs to the SESN family, known for its tumor-suppressing abilities." (PMID 39759146, 2024). "Further investigation of other transcripts in the pan-drug signature reveal that most have a known tumor suppressive function but others such as PRDM1, SESN1/2 may play a complicated or multiplex role in CRC and other cancers." (PMID 34611476, 2021). "Inactivation of Sesn1 has no additional effects on tumor growth and the lifespan of Sesn2-/-;KrasLSL-G12D mice." (PMID 31857853, 2019).
tumor (continued). "Accordingly, we demonstrated that the inactivation of the SESN1 and/or SESN2 genes by the CRISPR/Cas9 system accelerates cell proliferation in A549 cells and this mechanism may be responsible for tumor growth." (PMID 31857853, 2019). "We analyzed whether inactivation of the SESN1 and/or SESN2 genes may affect cell proliferation that can be responsible for the acceleration of tumor growth." (PMID 31857853, 2019). "Therefore, we proposed that SESN1 and SESN2 are potential tumor suppressors of lung carcinogenesis as their expression appeared to be consistently downregulated in the majority of NSCLC tumors relative to control lung tissues." (PMID 31857853, 2019). "Our recent study demonstrated that SESN1 and SESN2 might play an ambiguous role in lung carcinogenesis, supporting tumor growth at an early stage of carcinogenesis but suppressing cell proliferation and facilitating the death of tumor cells at an advanced stage." (PMID 39985075, 2025).
cancer (15 papers, 2015 to 2025). A tumor composed of atypical neoplastic, often pleomorphic cells that invade other tissues. "Loss of heterozygocity (LOH) in Sesn1 (6q21) and Sesn2 (1p35) is also often observed in diverse human cancers." (PMID 25962159, 2015). "Therefore, restoration of Sestrin activity or STAT3 inhibition in SESN1&2-deficient cancer cells may be a potential strategy to improve the treatment outcome for patients with cancers bearing mutations in SESN1 or SESN2 genes." (PMID 39985075, 2025). "Our previous data indicate that SESN2 supports cell death in response to genotoxic chemotherapeutic drugs, and inactivation of SESN1&2 in cancer cells potentially provides resistance to cell death induced by DNA damage." (PMID 39985075, 2025). "In the present study, KEGG enrichment analysis of the RNA‐seq data showed that PD‐L1 expression and PD‐1 checkpoint pathway in cancer was enriched in the four NB cell lines transfected with SESN1 siRNA #1 and siRNA #2." (PMID 38516781, 2024). "RNA‐Seq showed that Toll‐like receptor (TLR) signaling pathway, and PD‐L1 expression and PD‐1 checkpoint pathway in cancer were potential downstream targets of SESN1." (PMID 38516781, 2024). "AMPK is further activated through Sestrin-1 (SESN1), this latter being a critical factor at the interface between metabolism and cancer." (PMID 28698800, 2017). "Our study demonstrates that SESN1&2 deficiency may cause STAT3 activation and facilitate carcinogenesis and drug resistance, making SESN1&2 reactivation a potential cancer treatment strategy." (PMID 39985075, 2025). "Furthermore, miR-183-3p directly re-presses SESN1 and plays the biological function of promoting cancer in LUAD cells." (PMID 39759146, 2024). "Therefore, inactivation of SESN1/2 at the late stages of lung carcinogenesis might not contribute to suppression of AKT activity and may benefit cancer cells through mechanisms yet to be defined." (PMID 31857853, 2019).
degenerative diseases (1 paper, 2022). "The increased expression of SESN1 in progenitors highlights the effective role of physical exercise in degenerative diseases considering the protective role of sestrin." (PMID 36058924, 2022).
metabolic disorders (1 paper, 2025). "SESN1, the earliest discovered protein in the Sestrin family, is induced by environmental stressors such as oxidative stress, DNA damage, hypoxia, and starvation and plays a protective role in metabolic disorders." (PMID 40281957, 2025).
SESN1 also shares sentences with these, for which no sentence is quoted: infection (2 papers); liver disease (2); colitis (1); colorectal cancer (1); endothelial dysfunction (1); fibrosis (1); gastric cancer (1); heart disease (1); immune deficiency (1); inflammation (1); Insulin resistance (1); ischemia (1); polycystic ovary syndrome (1); prostate adenocarcinoma (1); skin cancer (1); spondylitis (1); Spondyloarthritis (1).